CD4 (CD4 molecule)
Diseases named in the same sentence as CD4 in open-access papers (continued):
Sharing a sentence is not in itself a finding about the gene and the disease.
tumor (continued). "Whole-body fractionated-LDI decreased tumor development and lung metastasis not only by infiltration of CD4+, CD8+ T-cells, and dendritic cells (DCs) but also by attenuating EMT." (PMID 32365904, 2020). "In ovarian cancer, TNFR1 enhances IL17+CD4+ T cell-dependent myeloid cell recruitment to tumor parenchyma leading to increased tumor growth." (PMID 33202705, 2020). "Additional studies have verified that DEX activates CD8+ and CD4+ T cells and induces an anti-tumor immune response by exosomal CD80 and endogenous IL-2 in vivo." (PMID 33183286, 2020). "RA produced by tumor DCs acts directly on CD4+ T cell cells, inducing Treg cell response while suppressing T effector cell response." (PMID 32132993, 2020). "It has been shown that the anti-tumor mechanism of anti-TIM3 requires CD4+ T cells and CD8+ T cells producing IFN-γ, and the model dependence on host CD11+ DC is relatively minimal." (PMID 33084973, 2020). "Immunohistochemistry was also performed on these tumor sections to evaluate the presence of tumor-infiltrating CD4+ Th and CD8+ Tcyt in the pFUS-treated tumors, compared to untreated control tumors." (PMID 32033171, 2020). "hetIL-15 directly affects NK, CD8+ and CD4+ T cells within the tumor promoting their proliferation, survival and cytotoxic commitment, with high levels of IFN-γ production and upregulation of GzmA, GzmB and perforin." (PMID 32461349, 2020). "A positive correlation was also noted for PD-L1 expression in tumor biopsies and both granzyme B and perforin in CD4+ helper T cells in peripheral blood, which characteristically express very low levels of these cytolytic granule-associated proteins." (PMID 33267869, 2020). "Downregulation of CD5 was associated with an increased fraction of activated CD4+ and CD8+ T cells in the tumor microenvironment." (PMID 33584650, 2020). "We also examined the tumor infiltrating lymphocytes (TILs) including CD4 and CD8 T cells and found that both A223 and KPPA tumors contained a much lower percentage of CD4 T cell than splenic controls." (PMID 32916850, 2020). "Zdanov and colleagues showed that KRAS-mutant tumour cells induced the conversion of CD4+ cells to Tregs." (PMID 33116132, 2020). "Cardiac histology of anti-PD-1-treated tumor-bearing mice demonstrated a dilated left ventricle, which was resulted by the infiltration of CD4+ and CD8+ T lymphocytes into the myocardium." (PMID 32244307, 2020). "CD8+ cytotoxic T cells (CTLs) and natural killer (NK) cells are primarily responsible for killing tumor cells, while CD4+ helper T cells can enhance their cytotoxic function by producing cytokines such as IFNγ." (PMID 33134306, 2020). "IP-10 (CXCL10) is regarded as a “key driver chemokine” attracting CD8+ and CD4+ T cells to tumor sites and potentiating their function." (PMID 32411122, 2020). "Another subset of CD4+ cells characterized by the production of IL-17 (Th17) has been shown to play a pro-tumor role in PC, where both tumor-infiltrating Th17 CD4+ cells and circulating levels of Il-17 and IL-23 correlated with advanced stage and worse OS." (PMID 32012917, 2020). "It is critical to customize CD4+ and CD8+ T cells for the purpose of tumor therapy or detection, because T cells can traffic through the circulatory system, and CD4+/CD8+ T cells play a major role in immunotherapy." (PMID 32358530, 2020). "The effect of anaphylatoxins on tumor-infiltrating CTLs remains unresolved, whereas several studies highlight the importance of CD4+ T cells in response to anaphylatoxins." (PMID 32733461, 2020). "In the same groups, the highest increase in IL-10 was observed, which is important for the normal function of helper CD4+ lymphocytes, CD4+ lymphocyte-mediated immune response, and suppression of tumor-mediated inflammation." (PMID 33126765, 2020).
tumor (continued). "Is the adequate antigen availability to prime and stimulate naïve CD4+ Th cells generated by CIITA-driven MHC-II expressing tumor cells useful in clinical setting for novel strategies of anti-tumor therapy?" (PMID 33138029, 2020). "The release of DAMPs results in increase in serum lympohocytes and incites CD4+ and CTLs and NK cells in tumour parenchyma, which shift the scale of balance towards an anti-tumour immune response rather from an tumour suppressive state." (PMID 32466214, 2020). "In this study, mice treated with either Ad-ΔB7/IL-12 or Ad-ΔB7/IL-12/4-1BBL have a higher amount of tumor infiltrating CD4+ and CD8+ cells in comparison to treatment with Ad-ΔB7/4-1BBL or Ad-ΔB7." (PMID 32050597, 2020). "Our present study further revealed that T cells CD4 memory activated were correlated with increased OS and play vital roles in anti-tumor process." (PMID 33043974, 2020). "InfDCs in tumor ascites induce autologous memory CD4+ T cells to differentiate into Th17 cells and Th1 cells." (PMID 32052078, 2020). "Nevertheless, the existing experimental evidence supporting the important role of CD4 T cells is compelling, by promoting and providing help to innate and adaptive anti-tumor immune responses." (PMID 33329566, 2020). "In a CatS Y132D transgenic mouse model of follicular lymphoma, they observed increased cancer growth versus wild-type controls and an increase of the tumor-suppressive CD4+ Treg over cytotoxic CD8+ T cells infiltrating the tumor." (PMID 32887380, 2020). "On the other hand, in PC pro-tumor Th2 CD4+ (GATA3+) sub-populations are more represented than the tumor-killing Th1 (T-bet+) and their levels correlate with poor prognosis." (PMID 32012917, 2020). "Several studies have suggested increase of CD4+CD25+ regulatory T cells among the splenocytes of tumor bearing mice and its correlation with increasing tumor burden." (PMID 32306719, 2020). "In turn, effector Th1 CD4+ T cells strengthen the normalization of tumor blood vessels by increasing the coverage of blood vessels with pericytes." (PMID 33096748, 2020). "Although cytotoxic CD8(+) T cells mediate direct tumor cell killing, CD4(+) T helper (TH) cells are also important in tumor cell eradication, as CD4(+) CAR T cells exert significant cytotoxicity comparable to CD8(+) CAR T cells." (PMID 33303017, 2020). "CD4+ T cells differentiate into T helper cells (Th I or Th II) and stimulate natural killer cells (NK cells) and macrophages that eliminate tumor cells and release pro-inflammatory cytokines to initiate the inflammatory process." (PMID 33505987, 2020). "Intraclonal competition was also reported to regulate relative abundance of TN and TM CD4 T cells (and in the case of tumor/self Ag-specific naïve CD4 T cells)." (PMID 32973794, 2020). "Microglia and peripheral macrophages, which extensively infiltrate GBMs, are collectively termed GAMs; tumor-infiltrating lymphocytes mostly comprise CD4+ T cells, CD8+ T cells, and regulatory T cells (Tregs)." (PMID 32457755, 2020). "In contrast, the importance of CD4 immunity for anti-tumor responses is less recognized as a result of limited studies." (PMID 33329566, 2020). "The significance of the demonstration that nivolumab causes an increase in the proportion of CD4+ cells that expressed Foxp3 within the peripheral blood compartment remains unclear since most of the existing literature has focused on CD4+FoxP3+ population within the tumor infiltrating lymphocytes." (PMID 32183719, 2020). "In vivo studies showed a remarkable increase in ICD manifest as an increase in both NK and activated CD8 and CD4 T cells in tumor tissues as well as calreticulin translocation." (PMID 33260534, 2020). "In our Multiplex IF analysis, PD-L1 expression was present mainly on tumor cells and macrophages, while PD-1 was expressed on CD4, and CD8 T cells." (PMID 32284756, 2020).
tumor (continued). "Higher abundance of tumor-infiltrating T follicular helper (Tfh) cells together with a lower abundance of resting memory CD4 T cells had been found in LUSC current reformed smokers for ≤15 years and current smoking patients." (PMID 33083119, 2020). "In contrast, the center of larger tumor formations (see areas marked with asterisks) showed relatively fewer T cells, particularly fewer CD4+ Th cells, if compared to tumor margins and smaller perivascular tumor cell groups." (PMID 33511078, 2020). "CD4 T cells differentiate into various T helper (Th) cell and regulatory (Treg) cell lineages to exert their functions in the tumor immunity." (PMID 33381115, 2020). "Of note, the major driving forces governing the accumulation of CD8+ or CD4+ tumor-reactive TILs in the TME are yet to be identified." (PMID 33198174, 2020). "CIITA-driven MHC class II-expressing tumor cells optimally stimulate in vivo tumor specific MHC class II-restricted CD4 T cells generating specific and long lasting protective immunity against the tumor." (PMID 33138029, 2020). "Disruption of H3K27 methyltransferase EZH2 activity in Tregs, drove the pro-inflammatory functions of TI-Tregs, remodelling the TME and enhancing the recruitment and function of CD8+ and CD4+ effector T cells that eliminate tumours." (PMID 32680511, 2020). "We used high-throughput sequencing to analyze the characteristics and changes of CD4+CD25+ TCR β CDR3 repertoires among tumor tissues, lung metastatic tissues, and spleens." (PMID 33029539, 2020). "Specific immune response was manifested by coproduction of IFN-γ/IL-2/TNF-α characteristic to the effector CD8+ and CD4+ T cells, which can eliminate tumor cells." (PMID 32570805, 2020). "In the present study, tumor expression levels of FAS, COX-2, and CD4 were associated with several other tumor characteristics." (PMID 32698885, 2020). "Owing to their ability to avoid thymic selection, TAAs can drive CTLs’ response in collaboration with CD4+ T cells to lyse tumour cells, and the degree of response is dependent on the frequency of mutations and likelihood of presenting T cell epitope." (PMID 32466214, 2020). "To further investigate the possible reasons for the reduced tumor control caused by B cell depletion, we analyzed the expression of CD69, IFN-γ and CD107a on both CD8+ and CD4+ T cell populations." (PMID 32929370, 2020). "PD-L1 expression by tumour cells can lead to evasion of the immune response by inhibiting T-cell responses through conversion of TH1 CD4 T-cells to Tregs." (PMID 32708945, 2020). "Samples taken from human cancer patients also showed the same pattern (Tregs >CD4+effectors > CD8+T cells) with highest OX40 expression on T cells isolated from tumor sites." (PMID 33428585, 2020). "The results showed that dual blockade of PD1 and LAG3 synergistically enhanced anti-tumor immunity by inhibiting tumor growth and enhanced infiltration of CD4+ and CD8+ T cells, combined with the increased production of IFN-γ and TNF-α." (PMID 33488573, 2020). "Profiling of tumor infiltrates revealed that anti-CTLA4 blockade increased the percentage of both CD4+ and CD8+ T cells in wild-type mice over isotype." (PMID 32641748, 2020). "Our previous study found that improved survival upon genetic loss of Erk5 in PtenΔ/Δ PCa model was related to increased levels of the T cell recruiting cytokines Ccl5 and Cxcl10 and enhanced T cell infiltration (predominantly CD4+) within the tumours." (PMID 31740786, 2020). "Some of these CD4 T cells possess anti-tumor activities, while others exert immunosuppressive activities mainly by regulating the CD8 response." (PMID 32244396, 2020). "An increase in the CD8/CD4 tumor-infiltrating T-lymphocyte (TIL) ratio was observed in the peptide–lipoplex-treated group and T cells in the spleen were KRAS-G12D-specific and did not respond to WT KRAS peptide." (PMID 33298945, 2020).
tumor (continued). "Using next generation technologies (e.g., RNA-sequencing, ATAC-sequencing), it is possible to unbiasedly define tumor-specific signatures both in effector cells (CD4+ and CD8+ T cells), regulatory T cells, and myeloid cells." (PMID 31974523, 2020). "In contrast to the findings of numerous analyses of the tumor properties of TETs, the present study involved experiments that focused on the T-cell properties of TETs, specifically for CD4 and CD8 single-positive T cells." (PMID 32132638, 2020). "Copy number variation of ACAA1 also pointed to lower abundance of CD4+ in the tumor microenvironment." (PMID 33194642, 2020). "Here, six tumor-infiltrating immune cells (B cells, CD4 T cells, CD8 T cells, macrophages, neutrophils, and dendritic cells) were considered." (PMID 32081859, 2020). "In mouse tumor models expressing human NIS (hNIS), repeated DNA vaccination with hNIS induced NIS associated CD4 and CD8 T-cell immune response along with improved efficacy." (PMID 32327728, 2020). "Recently, AnxA5 expression in CD4 T cells has been shown to be involved in regulatory function and anti-tumor immunotherapy." (PMID 33644036, 2020). "CTLA-4-mediated Treg depletion increases the Teff/Treg ratio within the tumor microenvironment and is associated with enhanced effector phenotypes of CD8 and CD4 cells in the tumor microenvironment." (PMID 32467593, 2020). "The initial population is composed of 80% of tumor cells, 10% of dendritic cells, and 5% of inactive CD4+ and CD8+ cells." (PMID 33281620, 2020). "As discussed later in greater detail, our downstream analysis, using all the selected LVs and tumor deconvolution techniques, identified the enrichment of M2 macrophage and CD4+ T cell markers as tumor microenvironment components in our samples." (PMID 32098059, 2020). "We recently showed by single-cell RNA sequencing and experimental validation that TCR8+CD4+ T cells exhibited superior anti-tumor function in vitro and in vivo compared to TCR+ or TCR8+CD8+ T cells." (PMID 32570906, 2020). "After migrating to nearby lymph nodes, Mature DCs present tumor antigens and activate CD4+ and CD8+ T cells which will then migrate to tumor site and facilitate tumor cell killing." (PMID 32457939, 2020). "Tumor MHC-II expression was proposed to stimulate cytotoxic CD4 T-cell responses in a subset of patients." (PMID 33202676, 2020). "Neoantigen vaccination elicited polyfunctional de novo CD4+ and CD8+ T cell responses against neoepitope pools and induced an anti-tumor T cell response that discriminated between mutated antigens and the corresponding wild type epitopes." (PMID 32245497, 2020). "To evaluate the role of Blimp-1 on CD4-driven tumor control, we isolated CD4+ TILs from MCA205 tumors and dLNs from αCTLA-4-treated Prdm1fl/fl or Prdm1−/−Cd4cre mice and transferred them to MCA205-bearing Rag1−/− mice." (PMID 31924474, 2020). "In the current study, we observed an increase in the total number of T-cells, CD4+ T-cells, and memory T-cells following tumor rechallenge in treated GL261-mice surviving long-term." (PMID 33002018, 2020). "It has been reported that tumor infiltration by a subpopulation of CD4+ T cells with immunosuppressive properties predicted reduced survival in EOC." (PMID 33271935, 2020). "Distinct functional profiles, albeit without dramatic differences, were detected for CD8+ TILs, whereas profiling of CD4+ TILs resulted in largely overlapping results across tumor types." (PMID 33198174, 2020). "Circulating CD4+CD25+ Tregs are trafficked into the tumor by the liver-specific chemokine receptor CCR6 and attracted by CCL20, secreted by HCC cells." (PMID 33036244, 2020). "In our previous studies, we have reported that tumor immune escape mechanism mediated by CD4+CD25+ regulatory T cells (Tregs) and inhibitory cytokine IL-35 is a key factor for the proliferation and apoptosis of leukemic blasts." (PMID 33415170, 2020).
tumor (continued). "One of the reasons for this discrepancy is that TILs are a heterogeneous cell population containing both tolerogenic regulatory CD4+FoxP3+ T cells (Tregs) and tumor recognizing CD8+ effector T cells." (PMID 33086518, 2020). "Localization of tumor-infiltrating CD4+ T-cells demonstrated inconsistent appearance in both B16 and 4T1 tumors following sonication." (PMID 32033171, 2020). "T CD4 memory predominated over CD8 within tumor infiltrating T lymphocytes (TILs) at that time, while M2 macrophages were the principal subpopulation among myeloid cells." (PMID 32354143, 2020). "Activated Treg cells also evade tumor immunity by inhibiting effector cells, such as CD4+ and CD8+ T cells." (PMID 32408477, 2020). "First, we noted that G-CSF was produced by both MC38 tumor cell and CD4+ T cell cultures by both WT and G-CSFR−/− T cells, suggesting the cytokine is present in the culture to act on the T cells." (PMID 33042110, 2020). "In particular, we will illustrate how at the tumor site CD4+ and CD8+ T cells, via production of key inflammatory cytokines, exert an active role in supporting inflammation and mediating tumor progression and escape." (PMID 32391271, 2020). "An increase of CD4+ Th1/Th2 cells and tumor-specific antigen expression by CD8+ T cells has been outlined on a molecular basis, as elaborated in the next paragraph." (PMID 32532074, 2020). "CD4+ Th cells can recognise tumour cells via binding to MHC class II molecules (MHC II) complexed with neoantigens." (PMID 32183246, 2020). "With inflammatory cytokines, including IFNγ, being produced in tumors and tumor-draining LNs, this study suggests that human LN LECs dampen tumor-specific CD4+ T cell activation in vivo." (PMID 33096748, 2020). "The number of distant tumour-infiltrating not only CD11c+ and OX-62+ DCs but CD4+ T cells in the RFA-OK-432 group was also higher than that in the OK-432 group." (PMID 32541941, 2020). "Both CD8+ and CD4+ cells contributed to an anti-tumor effect induced in a mouse model of HCC by immunization with ASPH-loaded DCs." (PMID 32811566, 2020). "CCR7 expression on CD4+ T cells of healthy subjects and tumor patients remained stable over age, but its expression was significantly lower in tumor patients (p < 0.01) as compared to healthy volunteers and in TIL compared to PBL of tumor patients (p < 0.05)." (PMID 32082401, 2020). "As CD4+ memory T cells are the most abundant immune cells in tumor tissues, more research into their role in tumor metastasis and disease progression is necessary; these cells represent a potential target for immune therapy." (PMID 33117674, 2020). "Understandably, tumor-infiltrating Tregs suppress the tumor-specific immune effector cells such as CD4+ T cells, cytotoxic CD8+ T cells, NK cells and DCs, and thus perturb the antitumor response of host." (PMID 33148302, 2020). "In contrast, cytokine neutralization significantly reduced numbers and proliferation of CD8+ Teff and CD4+ Teff, as well as numbers of NK cells in the tumor, indicating the specific depleting action of IFN-γ and TNF-α on Tregs versus Teff subsets." (PMID 32005826, 2020). "In fact, several epitopes presented by tumor cells and recognized by both CD4 + and CD8 + T cells have been identified." (PMID 33299117, 2020). "Indolent T-cell lymphoproliferative disease of the gastrointestinal tract (indolent GI T-LPD) is a benign neoplasm of CD4+ or CD8+ T cells that form primary tumors in the GI tract." (PMID 32850389, 2020). "When looking into the soluble inhibitory receptor of IL-22, a decrease in the amount of IL-22BP producing CD4+ T cells in the tumor tissue was found." (PMID 32100077, 2020). "In melanoma, the ex vivo depletion of CCR4(+) T cells from the peripheral blood of patients and subsequent in vitro stimulation of the depleted cell population with a tumor antigen, led to augmentation of antigen-specific CD4(+) T cells." (PMID 33203092, 2020).